EGFR (epidermal growth factor receptor)
Diseases named in the same sentence as EGFR in open-access papers (continued):
Sharing a sentence is not in itself a finding about the gene and the disease.
biliary tract cancer (26 papers, 2010 to 2026). "Recent research has indicated that EGFR and B7H3 antigens are highly expressed in biliary tract cancer, EGFR-CAR-T and B7H3-CAR-T cells demonstrated specific anti-tumor activity." (PMID 40013133, 2025). "Among biliary tract cancers, EGFR‐amplified cancers are known to be rare fractions across organs and have a poor prognosis." (PMID 39540676, 2024). "This clinical trial aims to generate a CAR-EGFR-TGFβR-knockout T by deleting TGF-receptor II using CRISPR/Cas9, to study its anti-tumour activity and safety profiles in EGFR-positive advanced unresectable or metastatic biliary tract cancer, previously treated." (PMID 37686639, 2023). "For example, overexpression of the receptor tyrosine kinase epidermal growth factor receptor (EGFR) has been implicated in metastatic colorectal and biliary tract cancers." (PMID 32082487, 2020). "In another study, Guo and colleagues observed that CAR T anti-EGFR cell immunotherapy was a safe way to treat EGFR-positive advanced biliary tract cancers." (PMID 32823711, 2020). "The epidermal growth factor receptor (EGFR) signaling pathway regulates biliary epithelial cell growth, and EGFR is overexpressed in biliary tract cancers." (PMID 28166242, 2017). "Since lapatinib is an oral dual kinase inhibitor of EGFR and Her-2/neu, an antitumor effect of this agent against biliary tract cancer was expected." (PMID 24212807, 2011). "Some studies have demonstrated overexpression of EGFR and VEGFR, or mutations of their signaling pathways in biliary tract cancer." (PMID 24212807, 2011). "EGFR expression has been reported in 67–100% of biliary tract cancers." (PMID 41340108, 2025). "Some preclinical experiences show that VEGFR or EGFR inhibitors administered alone might be effective in the treatment of biliary tract cancer." (PMID 24212807, 2011). "Thus, monotherapy with anti-EGFR inhibitors as first-line therapy may yield only minimum antitumor activity against biliary tract cancer." (PMID 24212807, 2011). "Furthermore, the expression status of various key molecular targets, such as KRAS, B-raf and MEK, should be examined to identify patients with biliary tract cancer who may benefit from treatment with anti-EGFR monoclonal antibody." (PMID 24212807, 2011). "At present, a clinical trial (NCT03093870) is ongoing to investigate the safety and efficacy of capecitabine in combination with varlitinib, an inhibitor of EGFR, HER2 and HER4, for the treatment of biliary tract cancer." (PMID 37814942, 2023). "Erlotinib is an orally active, potent, selective inhibitor of EGFR/HER1 tyrosine kinase, and a phase II study of erlotinib for unresectable biliary tract cancer has been reported." (PMID 24212807, 2011). "Recently, addition of the anti-EGFR antibody cetuximab to gemcitabine plus oxaliplatin did not enhance the efficacy of chemotherapy in patients with advanced biliary tract cancers in a randomized phase II trial." (PMID 28166242, 2017). "Recently, anti-epidermal growth factor receptor (EGFR) agents, mitogen-activated protein kinase/extracellular-signal regulated kinase (MEK) inhibitors, and anti-angiogenic agents have been thought to be the promising targeted agents for biliary tract cancer." (PMID 24131658, 2013). "The results of this trial (response rate of 17% and median overall survival of 7.5 months) suggested a therapeutic benefit of EGFR blockade with erlotinib in patients with biliary tract cancer, however, no further investigation was conducted." (PMID 24212807, 2011).
kidney cancer (26 papers, 2009 to 2025). Primary or metastatic malignant neoplasm involving the kidney. "In summary, our study confirms a previously known association between EGFR somatic mutations and East Asian ancestry, and is the first to systematically demonstrate a similar association in breast, prostate, and kidney cancers." (PMID 41162424, 2025). "Its presence in the germinal state suggests that the patients with kidney cancers carrying a homozygous mutation (A/A) are intrinsically resistant to EGFR inhibitors." (PMID 31938054, 2020). "(C) Cox proportional hazard regression analysis of the association between ALDH7A1 mRNA and EGFR levels for liver and kidney cancer." (PMID 30486822, 2018). "Pan-cancer analysis of East Asian ancestry and EGFR also found higher frequency in prostate, thyroid, and kidney cancers." (PMID 41162424, 2025). "Methylation and EGFR inhibition also yielded different effects in transporter expression, highlighting the regulatory disparity between cell lines representative of kidney cancer." (PMID 36077583, 2022). "Glucose uptake induces PD-L1 expression and PD-L1-mediated immune escape in the malignant kidney tumor microenvironment via the EGFR/ERK/c-Jun pathway." (PMID 36109724, 2022). "We show that reduction of the expression of either EGFR or TGFα by RNAi reduced proliferation of kidney cancer cells." (PMID 34399807, 2021). "Comparative RNAseq data of the 37 kidney cancer cell lines represented in such database showed expected variability among their EGFR and TGFA mRNA levels and copy number." (PMID 34399807, 2021). "EGFR inhibitors and TKIs have been applied in the clinical treatment of some tumours and have achieved significant therapeutic effects on kidney cancer patients, but some patients are resistant." (PMID 33462221, 2021). "The expression and prooncogenic functions of the EGFR and TGFα in kidney cancer have already been reported, but only strategies acting on the EGFR have been tested in the clinic." (PMID 34399807, 2021). "Data obtained from that database confirmed that the EGFR was highly expressed in kidney cancer cell lines, quantitatively ranking as the third tumoral type, behind upper aerodigestive tract and esophagus." (PMID 34399807, 2021). "Analyses of paired normal-tumoral patient samples showed that active EGFR and TGFα are frequently expressed in kidney cancer." (PMID 34399807, 2021). "In the case of the GEPIA2 database, kidney cancer ranked third of 33 different tumor types, with respect to EGFR amount." (PMID 34399807, 2021). "The recent development of immune checkpoint inhibitors for kidney cancer strongly suggests that IFN, the first generation of immuno-therapies, is a key player for combined treatment and should be associated with anti-EGFR inhibitors for a maximal effect." (PMID 31938054, 2020). "Given that S100A8 acts as an upstream target of EGFR signaling, anti-EGFR therapies, including midostaurin, enzastaurin and gefitinib has been proposed as potential therapy for kidney cancer cells which overexpressed S100A8." (PMID 28183295, 2017). "Expression of S100A8 and EGFR in kidney cancer among Saudi patients (CEGMR dataset) and GEO dataset (GSE781, GSE6344 and GSE7023)." (PMID 25789858, 2015). "Several studies using EGF receptor (EGFR) inhibitors have indicated that EGF/EGFR signaling mediates osteolytic bone metastasis of breast, prostate, and kidney cancers." (PMID 22209887, 2012). "To explore whether the TGFα/EGFR axis could play a role in the pathophysiology of kidney cancer, we used genetic and pharmacologic approaches to explore the effect of targeting the EGFR on the proliferation of kidney cancer cells." (PMID 34399807, 2021). "In fact, the cell proliferation data obtained by genetic as well as the pharmacologic targeting of EGFR and TGFα suggest that acting on this system may be used therapeutically in kidney cancer." (PMID 34399807, 2021).
kidney cancer (continued). "On the other hand, that high grade of uncertainty motivated us to preclinically explore the role of EGFR and TGFα in kidney cancer, as they could be used as druggable targets." (PMID 34399807, 2021). "The EGFR-TGFα axis plays a relevant role in the pathophysiology of kidney cancer." (PMID 34399807, 2021). "EGFR activation up-regulated PD-L1 expression through the ERK1/2/c-Jun pathway in non-small cell lung cancer (NSCLC), and glutamine modulated PD-L1 expression through the EGFR/ERK/c-Jun pathway in kidney cancer." (PMID 37420173, 2023). "This study found and confirmed for the first time that MIAC directly binds to AQP2 inhibiting the expression of EREG, EGFR and the activation of downstream PI3K/AKT and mTOR signaling pathways to achieve the inhibitory effect of kidney cancer growth and metastasis." (PMID 36117171, 2022). "Moreover, CDK4, EGFR, and MAP2K2 exhibited moderately high expression levels in cancer cells, with drugs targeting such therapeutic molecules presenting encouraging results in cancer therapy, but their clinical applications in kidney cancer are rarely reported." (PMID 38944814, 2024).
laryngeal carcinoma (26 papers, 1996 to 2025). Carcinoma that arises from the laryngeal epithelium. "This is explained by the fact that there is an overexpression of the epidermal growth factor receptor (EGFR) cascade in individuals with a history of cannabis smoking who have been diagnosed with laryngeal carcinoma." (PMID 38256042, 2024). "Cetuximab is an anti-EGFR monoclonal antibody, and has been found to effectively treat laryngeal cancer." (PMID 37542131, 2023). "Combination with the anti-epidermal growth factor receptor (EGFR) monoclonal antibody nimotuzumab was reported to result in increased antitumor efficacy in laryngeal cancer models." (PMID 33535479, 2021). "Survival analysis suggests that high expression of EGFR and INHBA is significantly associated with poor prognosis for laryngeal cancer." (PMID 34093817, 2021). "Based on these data, the Hellenic Cooperative Oncology Group (HeCOG) proceeded with evaluating the prognostic value of the VEGF, EGFR and insulin signaling pathways in laryngeal cancer." (PMID 23950933, 2013). "In this study we demonstrated that high EGFR levels single out patients with poor prognosis in laryngeal cancer." (PMID 8883413, 1996). "EGFR inhibition enhances radiosensitivity in laryngeal carcinoma, improving radiotherapy outcomes." (PMID 40370437, 2025). "Furthermore, cetuximab, an anti-EGFR monoclonal antibody, was found to reinforce oridonin-induced apoptosis by ER stress and mitochondrial pathway in laryngeal cancer 27-28." (PMID 38464825, 2024). "High levels of EGFR can indicate patients with laryngeal cancer with a poor prognosis." (PMID 25997441, 2015). "EGFR is overexpressed in approximately 90% of HNSCC cases, and its aberrant activation in laryngeal carcinoma promotes uncontrolled proliferation, radiotherapy resistance, and poor prognosis." (PMID 40370437, 2025). "This suggests that EGFR and INHBA can serve as prognostic hub genes for laryngeal cancer collectively with pRS genes (CFLAR, DAPK2, TSC2, CAPN10, MBTPS2, PEX14, FADD and ST13)." (PMID 34093817, 2021). "Among them, EGFR and INHBA were found to be significantly correlated with laryngeal cancer patient prognosis, HSA2 expression and pRS score." (PMID 34093817, 2021). "Analogous phenomenon was noticed by Lee and co-workers who showed that ME22S (a novel EGFR/MET bispecific antibody) significantly inhibited HGF-stimulated migration and invasion of laryngeal carcinoma cells." (PMID 31649529, 2019). "Our study suggests that EGFR and INHBA from fibroblasts may lead to malignant transformation of laryngeal cancer." (PMID 34093817, 2021). "High VEGFA expression, especially in combination with high EGFR expression has earlier been linked to local recurrence in TSCC in one study, and likewise in oral and laryngeal cancer, but not in a third study, including HPV-positive and HPV-negative OPSCC." (PMID 29587383, 2018). "Nevertheless, with respect to squamous-cell cancer of the head and neck, EGFR is among the best-studied examples, and positive and negative correlations between EGFR levels and tumor recurrences were reported in laryngeal cancers after radiotherapy." (PMID 15967033, 2005).
papillary thyroid cancer (26 papers, 2010 to 2026). "EGFR mutation was found in 71.4% of papillary thyroid carcinoma and 28.6% of follicular carcinoma." (PMID 36510281, 2022). "In our previous work, we demonstrated that miR-7-5p is significantly downregulated in papillary thyroid cancer and regulates the expression of epidermal growth factor receptor (EGFR) in thyroid neoplasms." (PMID 40565276, 2025). "MIG6 inactivation can be the result of loss of heterozygosity or focal deletion of ERRFI1, as reported in EGFR-amplified glioblastoma, or promoter methylation, as found in papillary thyroid carcinoma." (PMID 26788993, 2016). "Accordingly, MIG6 down-regulation in thyroid cancer cells and papillary carcinoma enhances EGFR, ERBB2 and MET activity." (PMID 26788993, 2016). "Notably we also identified one papillary thyroid carcinoma of follicular variant with both KRAS and EGFR mutation." (PMID 36510281, 2022). "More recently, it has been reported a patient with metastatic poorly differentiated thyroid carcinoma with an EGFR mutation who responded to treatment with the selective EGFR TKI (tyrosine kinase inhibitor) erlotinib, strongly suggesting the importance of EGFR as therapeutic target in DePTC." (PMID 25789503, 2015). "In papillary thyroid cancer, METTL14 regulates miR‐98 expression by inhibiting OIP5‐AS1 expression and activates epidermal growth factor receptor (EGFR), MEK/ERK pathways to inhibit proliferation and migration/invasion of papillary thyroid cancer cells." (PMID 38263865, 2024). "Wang argued that GALNT7 by activating EGFR/PI3K/AKT kinase pathway to promote cell proliferation and invasion of papillary thyroid cancer." (PMID 36276977, 2022). "Overall, miR-30b-5p inhibited the progression of papillary thyroid carcinoma by targeting GALNT7 and inhibiting the EGFR/PI3K/AKT pathway." (PMID 34819077, 2021). "Papillary thyroid cancer model TPC-1 did not express p-EGFR under any of the tested conditions (data not shown), whereas ErbB2 protein was always expressed and particularly increased after PD and EGF alone treatments." (PMID 35269445, 2022).
cutaneous melanoma (25 papers, 2004 to 2025). A primary melanoma arising from atypical melanocytes in the skin. "These alterations appear to be particularly relevant in acral and mucosal melanomas, which are underrepresented in the TCGA’s cutaneous melanoma cohort, but show a higher prevalence of EGFR and PIK3CA mutations." (PMID 40652269, 2025). "The fourth highest EGFR mutation frequency in their study is skin cutaneous melanoma in which approximately 6% carry mutations in EGFR." (PMID 37333807, 2023). "Increased copy number for EGFR and chromosome 7 alterations have been reported in primary cutaneous melanoma to be associated with poor prognosis." (PMID 24281094, 2010). "In addition, an increased proliferative index was associated with a decreased EGFR expression in the skin melanomas." (PMID 33664868, 2021). "Furthermore, in 114 patients with primary cutaneous melanomas, EGFR expression was found to be associated with metastatic spread to sentinel lymph nodes and the presence of EGFR polysomy was correlated with thicker primary tumors." (PMID 27102439, 2016). "Alteration in the gene copy number of EGFR has been related to poor survival in cutaneous melanoma, and HER-2 overexpression has been described in thick cutaneous melanomas (thickness ≥ 10 mm), even if without proven prognostic significance." (PMID 38791617, 2024). "In human medicine, EGFR expression in metastases from primary cutaneous melanomas has been suspected to have a prognostic significance." (PMID 38791617, 2024). "In Riker’s dataset, ERBB1 (EGFR) is under-expressed in cutaneous melanoma with a fold change of −8.110." (PMID 33732282, 2021). "In cutaneous melanoma an increased proliferative index was associated with increased cytoplasmic HER4 and reduced EGFR and HER3 protein expression." (PMID 31996230, 2020). "Looking beyond combinations involving mutant EGFR or KRAS, we found that BRAF mutations in skin cutaneous melanoma (SKCM) were negatively associated with NRAS." (PMID 26047463, 2015). "EGFR also has potential as an important therapeutic target in human cancer because it may be involved in the progression of cutaneous melanomas specifically and more generally acts upstream of mTOR as a signal transducer of mitogens, which play a role in cancer pathogenesis and development." (PMID 36077992, 2022). "As high EGFR expression goes along with a poor prognosis in skin cutaneous melanomas, we further analyzed the effect of NRF2 on EGFR regulation." (PMID 33916908, 2021). "ERBB 1 (EGFR) induces the infiltrating levels of B cells, CD4+ T cells, Neutrophils, and Dendritic Cells in cutaneous melanoma." (PMID 33732282, 2021). "In summary, we identified a relationship between the proliferative index and both increased cytoplasmic HER4 expression and reduced EGFR and HER3 expression in skin melanomas." (PMID 31996230, 2020). "Higher EGFR expression correlated with decreased cytoplasmic HER2 expression (r: − 0.3357; p: 0.0422) in the skin melanomas." (PMID 31996230, 2020). "The four ERBB tyrosine kinase family members [ERBB1 (epidermal growth factor receptor, EGFR), ERBB2 (HER2), ERBB3 (HER3), and ERBB4 (HER4)] (ERBB receptor family) have been shown, according to previous studies, to be related to the cutaneous melanoma." (PMID 33732282, 2021).
Parkinson disease (25 papers, 2012 to 2026). A progressive degenerative disorder of the central nervous system characterized by loss of dopamine producing neurons in the substantia nigra and the presence of Lewy bodies in the substantia nigra and locus coeruleus. "In a study with Chinese patients, two polymorphisms of the EGFR gene were associated with susceptibility to Parkinson’s disease." (PMID 40940805, 2025). "Decreased levels of EGF in plasma have also been reported in Parkinson’s (PD) and AD, limiting in this way EGFR activation." (PMID 40508163, 2025). "Using this platform, we demonstrate that over 50% of Parkinson’s-related N370S mutation in the GBA gene and cancer-related L858R mutation in the EGFR gene can be achieved after 7 days of doxycycline incubation." (PMID 39737975, 2024). "Thiazolopyridine compounds are able to act as antitumor agents and potential therapeutic agents for Parkinson’s disease, through inhibition of the epidermal growth factor receptor (EGFR) and monoamine oxidase B, respectively." (PMID 26536233, 2015). "EGFR positive cells have been reported to be depleted in SVZ in Parkinson's disease as well: these data collectively indicate a role of dopamine-EGFR signaling loop in regulation of neurogenesis of dopaminergic neurons." (PMID 22754566, 2012). "Advanced age, EGFR-mutant/PD-L1-high tumor biology, recent radiotherapy, and Parkinsonism may have contributed to the inflammatory environment, though none can be proven causal in a single case and each deserves prospective study." (PMID 42266672, 2026). "Regulation of EGFR endocytosis via parkin protein drives Parkinson’s pathology." (PMID 28792504, 2017). "Many signaling pathways including 14-3-3 mediated, neuregulin, semaphorin, ephrin, gap-junction, axonal guidance, as well as different growth factor signaling like EGF/EGFR, FGF, and NGF, were found enriched in Parkinson's disease pathology." (PMID 24688734, 2013). "Moreover, AZD 3759, a blood brain barrier permeable EGFR-tyrosine kinase inhibitor (EGFR-TKI), was found to reduce the phosphorylated α-synuclein levels, a pathological biomarker of Parkinson’s Disease." (PMID 40444141, 2025).